SHBG (sex hormone binding globulin)
Diseases named in the same sentence as SHBG in open-access papers (continued):
Sharing a sentence is not in itself a finding about the gene and the disease.
cervical cancer (1 paper, 2004). A primary or metastatic malignant neoplasm involving the cervix. "In contrast, our findings for total oestradiol, SHBG, oestrone, and free oestradiol fail to support the notion that high levels of oestrogens increase the risk of cervical cancer." (PMID 14710222, 2004).
cervical spondylosis (1 paper, 2024). "Education prevents the risk of cervical spondylosis by reducing SHBG." (PMID 38725482, 2024). "In further studies, when adjusted for education, only SHBG was still statistically significant in relation to cervical spondylosis." (PMID 38725482, 2024). "It is a good research direction to further explore the relationship between SHBG and cervical spondylosis in follow-up research." (PMID 38725482, 2024). "It was estimated that the proportion of educational mediated effects on cervical spondylosis through SHBG as (2.5%; [95%CI:0.2%-4.9%])." (PMID 38725482, 2024). "This may suggest to some extent that the effects of SHBG on education and cervical spondylosis are sex-related." (PMID 38725482, 2024). "In summary, this study elaborates the causal protective effect of education independent of intelligence and cognitive ability on cervical spondylosis, and outlines the causal mediating factors (SHBG) and factors that are causally associated with the onset of cervical spondylosis." (PMID 38725482, 2024). "After our MR analysis of SHBG, BMI and cervical spondylosis, we found that there was no clear causal relationship between SHBG and BMI, so BMI could not be used as an intermediary factor of SHBG for cervical spondylosis." (PMID 38725482, 2024). "And SHBG (β: 0.140; se: 0.046; p < 0.05; OR:0.87; [95%CI: 0.795–0.951]) and HDL-C (β: 0.101; se: 0.046; p < 0.05; OR:0.90; [95%CI: 0.826–0.990]) were protective factors of cervical spondylosis." (PMID 38725482, 2024).
colon cancer (1 paper, 2024). "Furthermore, according to the Women’s Health Initiative, individuals with the highest SHBG levels are more than twice as likely to develop colon cancer compared to those with the lowest SHBG levels." (PMID 39687887, 2024).
coronary artery stenosis (1 paper, 2006). "Correlations between different indices of coronary artery stenosis (A, B, C, A+B, and A × B) and the levels of blood lipids, sex steroid hormones, sex hormone binding globulin (SHBG) or free testosterone index (FTI)." (PMID 23674975, 2006).
diabetic retinopathy (1 paper, 2021). "However, higher FSH (P < 0.001), LH (P = 0.001), and SHBG (P = 0.001) levels were observed in the diabetic retinopathy group." (PMID 33575359, 2021). "The patients in the diabetic retinopathy group not only had significantly higher HbA1c, FPG, urinary ACR, and systolic blood pressure but also had higher FSH, LH, and SHBG levels compared to those in the non-DR group." (PMID 33575359, 2021).
endometrioid carcinoma (1 paper, 2022). "In addition, the serum levels of endogenous oestrogen and sex hormone binding globulin (SHBG) were different between patients with endometrioid carcinoma and patients with serous carcinoma, after adjusting for age and BMI." (PMID 35237786, 2022).
esophageal adenocarcinoma (1 paper, 2021). A malignant tumor with glandular differentiation arising predominantly from Barrett mucosa in the lower third of the esophagus. "Future studies may also investigate how FSH or SHBG levels change with the progression of esophageal adenocarcinoma to better inform potential therapeutic targets." (PMID 32895915, 2021).
esophageal squamous cell carcinoma (1 paper, 2025). Esophageal squamous cell carcinoma (ESCC) is a type of esophageal carcinoma (EC) that can affect any part of the esophagus, but is usually located in the upper or middle third. "Especially the C allele of rs727428 in SHBG is correlated with reduced risk of esophageal squamous cell carcinoma." (PMID 40427034, 2025). "SHBG SNPs are found to affect the risk of esophageal squamous cell carcinoma." (PMID 40427034, 2025).
Fanconi renotubular syndrome (1 paper, 2024). A genetic or acquired disorder characterized by impairment of the function of the proximal tubules of the kidney. "Biallelic variants in HNF1A can cause hepatocellular adenomas, while variants in HNF4A can cause Fanconi renotubular syndrome and are associated with SHBG levels." (PMID 39666780, 2024).
female reproductive cancers (1 paper, 2017). "With particular referral to female reproductive cancers, several mechanisms have been proposed: for instance, caffeine and coffee intake have been positively associated to sex hormone-binding globulin (SHBG) in postmenopausal women." (PMID 29120352, 2017).
glomerulopathies (1 paper, 2023). "As a result, a highly accurate classifier was developed (AUC = 0.99) that enables distinguishing between mild and severe glomerulopathies based on the assessment of only three urine proteins (GPX3, PLMN, and A1AT or SHBG)." (PMID 37110557, 2023).
glycogen storage disease type 1a (1 paper, 2022).
hemolysis (1 paper, 2025). Disruption of the integrity of the erythrocyte membrane causing release of hemoglobin. "Among the top 30 proteins with highest variance were 12 immunoglobulins (CV between 22.0% and 89.2%), 4 hemolysis-related proteins (CV between 26.9% and 54.5%) as well as the hormone transporters transcortin (SERPINA6, CV = 48.3%) and sex hormone binding globulin (SHBG, CV = 123.3%)." (PMID 40263456, 2025).
juvenile rheumatoid arthritis (1 paper, 2022). "High IMT values in PCOS were reported in women in early adulthood (associated with decreased sex hormone-binding globulin) and adulthood in obese women and patients with juvenile rheumatoid arthritis." (PMID 35327688, 2022).
large artery stroke (1 paper, 2025). Stroke caused by the blockage of blood flow in one of the large arteries feeding the brain. "Although the sample size of the GWASs was relatively large, our study did not detect a significant relationship between genetically determined SHBG levels with cardioembolic or large-artery strokes." (PMID 40728963, 2025).
Lung squamous cell carcinoma (1 paper, 2024). "Except for the causal relationships between Gamma_glutamyltransferase, SHBG, Sodium_in_urine and lung squamous cell carcinoma, the other seven causal relationships were all validated by five types of MR analysis, and generated consistent effect estimation directions." (PMID 39687887, 2024).
obstructive sleep apnea (1 paper, 2022). "Another study showed that lower levels of sex hormone-binding globulin (SHBG) are associated with increasing obstructive sleep apnea." (PMID 35634394, 2022).
Opportunistic infection (1 paper, 2025). An infection that is caused by a pathogen that would generally not be able to cause an infection in a host with a normal immune system. "The mechanisms include hypothalamic–pituitary–gonadal axis dysfunction, chronic inflammation, opportunistic infections, and elevated sex hormone-binding globulin (SHBG) that reduce bioavailable testosterone." (PMID 41295583, 2025).
ovarian endometriosis (1 paper, 2025). A non-neoplastic disorder characterized by the growth of endometrial tissue in the ovaries. "A later study by the same team of authors showed the dominant expression of a certain variant of SHBG mRNA associated with the peculiarities of exon VII splicing in ovarian endometriosis." (PMID 41373783, 2025).
overnutrition (1 paper, 2021). An imbalanced nutritional status resulting from excessive intake of nutrients. "Moreover, increased insulin associated with overnutrition reduces hepatic production of sex hormone-binding globulin (SHBG), which binds to estradiol." (PMID 34066392, 2021).
pituitary adenoma (1 paper, 2025). "Further investigations performed revealed a normal sex hormone-binding globulin (SHBG), a mildly elevated alpha-subunit, an exaggerated TSH in response to thyrotrophin stimulation, and the absence of a pituitary adenoma on magnetic resonance imaging (MRI)." (PMID 40027009, 2025).
Tauopathies (1 paper, 2021). "Our previous unbiased proteomics study revealed lower levels of sex hormone-binding globulin (SHBG) in the CSF of FTLD-Tau cases compared to FTLD-TDP or non-demented controls, suggesting that SHGB could be a potential biomarker for FTLD related tauopathies." (PMID 34680117, 2021).
teratoma (1 paper, 2025). A non-seminomatous germ cell tumor characterized by the presence of various tissues which correspond to the different germinal layers (endoderm, mesoderm, and ectoderm). "Pituitary hormone-coding PRL and GNRH1 peaked in teratoma, while SHBG mRNA levels were the highest in yolk sac tumors." (PMID 40011822, 2025).
testicular cancer (1 paper, 2012). A primary or metastatic malignant neoplasm that affects the testis. "Applying the method to testicular cancer, we found a nominally significant M×M interaction between single nucleotide polymorphisms from C-Kit Ligand (KITLG) and Sex Hormone Binding Globulin (SHBG) using 210 families (relative risk 2.2, P = 0.03)." (PMID 22740241, 2012).
thyroid hormone resistance (1 paper, 2022). "Investigations that support the diagnosis of TSHoma over thyroid hormone resistance include elevated α-subunit/TSH ratio (>1.0) and serum sex hormone-binding globulin level (peripheral tissue marker of thyroid hormone action)." (PMID 36004344, 2022).
Tourette syndrome (1 paper, 2025). A neurologic disorder caused by defective metabolism of the neurotransmitters in the brain. "Interestingly, we also observed a suggestive, nominally significant positive genetic correlation between SHBG and Tourette’s syndrome (p = 4.70 × 10−2)." (PMID 40727568, 2025).
Zinc deficiency (1 paper, 2020). A deficiency of the essential metal Zinc; an essential cofactor for many enzymes. "Additionally, in the case of testosterone deficiency syndrome, zinc deficiency seems to be one of the components of the pathomechanism due to the negative correlation with SHBG, causing the body’s access to free testosterone fractions." (PMID 32183007, 2020).
cancer (80 papers, 1985 to 2026). A tumor composed of atypical neoplastic, often pleomorphic cells that invade other tissues. "Its suppression by insulin via downregulation of HNF4α links hepatic metabolic status to systemic hormonal control, establishing SHBG as a key mediator at the intersection of metabolic dysfunction, hyperinsulinaemia, and cancer risk." (PMID 41586225, 2025). "SHBG downregulates the proto-oncogenes c-Myc, B-cell lymphoma-2 (Bcl-2), and growth factor receptors associated with cancer cell growth, proliferation and survival." (PMID 41586225, 2025). "There was potential sample overlap (which can compound weak instrument bias) in multivariable MR analyses evaluating evidence for a causal effect of ASAT adjusted for HDL cholesterol, SHBG, and bioavailable testosterone on cancer risks." (PMID 40987470, 2025). "According to our results, higher SHBG levels were associated with an increased risk of cancer mortality in men and all-cause mortality in women which were independent of free or bioavailable testosterone levels." (PMID 40333346, 2025). "In BC survivors, elevated levels of estrogen and testosterone correlate with higher cancer recurrence and mortality, whereas elevated SHBG levels are tied to a lower risk of death." (PMID 40699773, 2025). "An additional 30 loci were found to be associated with cancer risk and sex-hormone binding globulin levels." (PMID 38965614, 2024). "Another suggested pathway between glucose and risk of cancer is the reduced hepatic production of sex hormone binding globulin (SHBG) following prolonged hyperinsulinaemia." (PMID 25526881, 2014). "The observed association between high SHBG levels ang GC may be explained by the inhibition of estradiol’s anti-cancer properties, which are linked to its reduced bioavailability." (PMID 40929117, 2025). "Alterations in SHBG concentrations can therefore affect not only the circulating levels of active sex steroids but also their signalling activity within target tissues, influencing cancer susceptibility and progression." (PMID 41586225, 2025). "Lower levels of SHBG are also associated with increased incidence of cancer." (PMID 41586225, 2025). "Elevated sex hormone-binding globulin levels generally reduce the proportion of oestradiol in the body, thereby reducing the stimulation of breast cell proliferation by oestradiol and thus reducing the risk of cancer." (PMID 38547495, 2024). "Our GWAS findings supported the impacts of testosterone on both cancers’ susceptibility and suggested that sexual hormone traits such as SHBG or testosterone levels may be a key mediator of shared mechanisms between the two cancers." (PMID 37340002, 2023). "The exponentiated regression coefficient we observed for rs727428 [T] (eβ = 0.88 i.e. a 12% reduction in convariate-adjusted SHBG levels per T allele) is very similar to that found among postmenopausal women from the European Prospective Investigation of Cancer-Norfolk cohort study." (PMID 22675492, 2012). "Finally, 91 candidate genes that may be related to circulating SHBG concentrations and cancer risk were selected." (PMID 33595913, 2021). "Mediation analysis suggested that PDAP1 decreased longevity via decreased SHBG, increased waist circumference, blood pressure, smoking, and alcohol consumption in addition to cancer." (PMID 40211681, 2025). "SHBG is a sensitive biomarker of metabolic-endocrine status, with broader implications for cancer, and reproductive function." (PMID 41586225, 2025). "In contrast, a low SHBG setting results in cancer cells exhibiting increased levels of c-Myc expression, driving transcriptional programmes that promote cellular proliferation, aerobic fermentation, and dedifferentiation." (PMID 41586225, 2025). "In a study of adult men and women undergoing liver resection for cancer, our group reported a strong positive correlation between hepatic HNF4α and SHBG mRNA levels, and between SHBG mRNA in liver and circulating SHBG levels." (PMID 40863113, 2025).
cancer (continued). "These observed data are in agreement with previous findings that evidenced the implication of SHBG in various cancer cell proliferation inhibition." (PMID 38874666, 2024). "In this report, we showed the risk value for BC of SHBG-lowering allele variant C rs10454142 PPP1R21 (OR = 1.31) in Caucasian women in Russia, which determines 0.32% of the cancer variance." (PMID 38396861, 2024). "Lee and Hong demonstrated that SHBG suppresses human hepatocarcinoma cancer cell proliferation by targeting JNK/p38/ERK/AP-1 signals." (PMID 38874666, 2024). "The autocrine-paracrine growth factor, insulin-like growth factor 1 (IGF-1), has been reported to be a promoter of cancer that inhibits the sex hormone-binding globulin (SHBG) and exists in elevated levels in African American individuals." (PMID 37345032, 2023). "For cancer-related biomarkers, in white British participants, all other diet groups had higher serum SHBG than regular meat eaters, whereas vegetarians and vegans had lower IGF-I concentrations." (PMID 34132352, 2021). "SHBG positively correlates with HDL and negatively with TGs and has been already associated with different cancers in ageing humans." (PMID 33182326, 2020). "Randomized controlled trials (RCTs) were included if they compared any type of exercise intervention to no intervention or other interventions, and assessed the effects on estrogens, androgens or the sex hormone binding globulin (SHBG) in cancer-free women." (PMID 26541144, 2015). "The sex hormone-binding globulin (SHBG) level is one of the most important factors in cancer generation and/or development in postmenopausal women because its reduction leads to an increase in free ovarian steroid hormones." (PMID 25866823, 2015). "Real-time, quantitative PCR showed that SHBG transcription is tissue dependent, and perhaps, cancer dependent." (PMID 19416531, 2009). "Hyperinsulinaemia decreases SHBG levels, which increases c-Myc expression in cancer cells." (PMID 41586225, 2025). "SHBG and leptin, when interpreted in context, provide mechanistically grounded biomarkers that support timely metabolic intervention before the onset of pathology such as cancer progression." (PMID 41586225, 2025). "The risk genetic factor for BC developing is an SHBG-lowering allele variant C rs10454142 PPP1R21 ([additive genetic model] OR = 1.31; 95%CI = 1.08–1.65; pperm = 0.024; power = 85.26%), which determines 0.32% of the cancer variance." (PMID 38396861, 2024). "In addition to increasing cancer risk through IGF-1, insulin also influences carcinogenesis and progression by lowering sex hormone-binding globulin (SHBG) levels." (PMID 39290325, 2024). "For SHBG-related loci, pronounced functionality in the organism (including breast, liver, fibroblasts, etc.)was predicted in silico, having a direct relationship through many pathways with cancer pathophysiology." (PMID 38396861, 2024). "Research suggests that SHBG may play a role in the progression of these cancers by regulating the levels of hormones that promote cell growth." (PMID 37538932, 2023). "For total and calculated free testosterone, the expected inverse association with SHBG levels was observed only for “all-cause” and cancer mortality and not for CVD deaths." (PMID 34335746, 2021). "Of the covariates included in the main model (model 3), in the white British population, BMI adjustment partly attenuated the magnitude in the differences of most cardiovascular-related (all except HDL cholesterol) and cancer-related (SHBG, testosterone in men) biomarkers." (PMID 34132352, 2021). "Moreover, the indirect cancer-promoting function of insulin also includes the inhibition of SHBG (which can tightly bind estradiol and testosterone) production in liver, elevating free sex hormones (both androgen and estrogen) in serum." (PMID 32913460, 2020). "Indeed, studies suggest testosterone levels are lower and SHBG higher in male cancer cases compared to age-matched healthy men." (PMID 29342161, 2018).